SLC2A3 (solute carrier family 2 member 3)
Diseases named in the same sentence as SLC2A3 in open-access papers (continued):
Sharing a sentence is not in itself a finding about the gene and the disease.
tumor (continued). "Tumor growth was suppressed by silenced LINC01215 via reducing the expression of SLC2A3 via miR-184." (PMID 33173535, 2020). "We found that SLC2A3 knockdown in HCT116 tumours strikingly reduced the levels of glucose, pyruvic acid, lactate and many nucleotides, while ectopic expression of GLUT3 in RKO tumours significantly raised the levels of these metabolites." (PMID 32873793, 2020). "CD36 (p value < 2.22e-16), CPA3 (p value < 2.22e-16), NFATC1 (p value = 9.1e-08), and RASGRP2 (p value < 2.22e-16) were highly expressed and SLC2A3 (p value = 0.0015) was lowly expressed in tumor samples." (PMID 32908876, 2020). "As a tumor suppressor, miR-106a decrease glucose uptake and ATP production by affecting the expression of SLC2A3." (PMID 28750689, 2017). "In conclusion, we have shown that miR-106a is one of the tumor suppressor miRNAs and SLC2A3 is a novel and critical target of miR-106a in GBM." (PMID 24124917, 2013). "The genes of the SLC family such as SLC2A14 and SLC2A3 and the AKR1 (aldo-keto reductase 1) family such as AKR1C1, AKR1C2, AKR1C3 and AKR1B10 were associated with the metabolic processes of tumor cells." (PMID 20003295, 2009). "In most cancers, high SLC2A3 expression may drive glycolytic reprogramming and tumor proliferation, accelerating disease progression." (PMID 41268544, 2025). "Sh‐YTHDF2 and DNase I promoted SLC2A3 expression in tumours and had a superimposed effect." (PMID 39865544, 2025). "Similarly, in SLC2A3 protein expression, higher clinical stage and tumor grade had significantly higher SLC2A3 expression." (PMID 38778609, 2025). "This suggested that SLC2A3 may promote the expression of immune checkpoints in the tumor microenvironment, leading to a more robust immune suppression and an increased likelihood of immune escape." (PMID 38778609, 2025). "In HNSCC, its expression is negatively correlated with the number of CD8+ T cells and resting dendritic cells, suggesting that SLC2A3 may promote tumor progression by inhibiting immune cell function." (PMID 40821122, 2025). "In HNSCC, SLC2A3 expression is negatively correlated with various immune cell types, suggesting it may promote tumor progression by suppressing anti-tumor immunity." (PMID 41268544, 2025). "Additionally, SLC2A3 was enriched in the EMT pathway, which is closely linked to tumor development and metastasis." (PMID 38778609, 2025). "As a high-affinity glucose transporter, the overexpression of SLC2A3 may further enhance glucose uptake and glycolytic flux, providing an energy advantage for tumor cells in hypoxic environments." (PMID 41268544, 2025). "Our results indicate that inhibiting SLC2A3 may impair metabolic adaptation, decrease tumor heterogeneity and stemness, and improve responses to immunotherapy." (PMID 41268544, 2025). "Both glucose uptake and the expression of the glucose transporter Glut1 (Slc2a1), but not that of Glut2 (Slc2a2), Glut3 (Slc2a3), or Glut4 (Slc2a4), were elevated in Cpt1a-deficient ErbB2 tumor cells." (PMID 39097623, 2024). "The effect of SLC2A3 on tumor growth and metastasis was tested in vivo." (PMID 38625978, 2024). "Herein, we further investigated the association between glycolysis and IDO1 in PC with bioinformatic analysis and found the expression of SLC2A1, SLC2A3, SLC2A5 (encoding GLUT1, GLUT3, GLUT5 protein), and IDO1 in the tumor tissues of PC patients was increased compared to the adjacent normal tissues." (PMID 38706741, 2024). "Notably, SLC2A3 expression was highly induced in the perinecrotic/hypoxic area of GBM tumor sections, while exhibiting relatively sparse expression in LGG tumors that inherently lack perinecrotic regions." (PMID 38414005, 2024). "Moreover, 2‐DG and 3‐BP, as well as SLC2A3 and PGAM1 down‐regulation, reversed the acceleration of tumor growth caused by METTL14 knockdown." (PMID 36794620, 2023).
tumor (continued). "However, both SLC2A1 (FDR < 0.01) and SLC2A3 (FDR < 0.001) genes—associated with higher glucose uptake and oncogenic growth —are markedly overexpressed in BRAF- (vs RAS)-like tumours." (PMID 37198319, 2023). "For instance, SLC2A3, a glucose transporter, could promote the growth and spread of the tumor by intensifying glucose uptake upon overexpression." (PMID 37702857, 2023). "The upregulation of the novel doxorubicin importer SLC2A3 would directly increase the uptake of doxorubicin in K562 and 293T cells, and result in the better killing of these tumor cells." (PMID 37523060, 2023). "Finally, the hub gene SLC2A3 was found exclusively upregulated in extracellular matrix-related CSCs, predicting prognosis, and shaping an immunosuppressive tumor microenvironment." (PMID 36902193, 2023). "SLC2A3 was significantly upregulated in 43 tumor tissues than in paired normal tissues (P < 0.001)." (PMID 36247875, 2022). "Similarly, the high expression level of SLC2A3 was also a poor prognostic factor in the II–IV subgroup of tumor pathological staging (p = 0.011)." (PMID 35957685, 2022). "Additionally, lower levels of SLC2A3, SLC2A6, SLC2A9, SLC2A12, and SLC2A14 and higher levels of SLC2A1, SLC2A5, SLC2A10, and SLC2A11 had an association with advanced tumor stage." (PMID 36518662, 2022). "In addition, we found that SLC2A3 was positively related to stromal, immune, and ESTIMATE score associated with tumor invasion." (PMID 36247875, 2022). "Furthermore, immunohistochemistry staining analysis showed that SLC2A3 expression was significantly higher in CRC compared with that in the adjacent non-tumor colorectal mucosa tissues." (PMID 34211835, 2021). "Notably, recent studies revealed that tumor-Infiltrating Lymphocytes (TILs) in CRC tumor bed have been interrelated with favorable outcome, we were curious about the effect of SLC2A3 expression on TILs in CRC." (PMID 34211835, 2021). "CSCs reside in a tumor mass where they often encounter hypoxic conditions and glucose deprivation, therefore, it is possible that the SLC2A3 upregulation may respond to the microenvironment of CSCs." (PMID 32592372, 2020). "Results showed that tumors could be detected in both SLC2A3-LV and Control-LV mice and mice in the SLC2A3-LV group had larger tumor volumes than the control mice." (PMID 33061855, 2020). "Positive SLC2A3 staining results have been reported in several malignant tumor tissues, suggesting that SLC2A3 may participate in facilitating glucose uptake in tumors with intense glucose requirements." (PMID 33061855, 2020). "Here, we show that SLC2A3 acts as a tumor promoter and accelerates aerobic glycolysis in GC cells." (PMID 33061855, 2020). "Therefore, our study provides insights into understanding the potential role of SLC2A3 in tumor immunology and its use as a GC biomarker." (PMID 33061855, 2020). "Also, we found higher transcript levels of SLC2A1 and HK2 in C-PDAC tumours relative to EL-PDAC tumours and the highest SLC2A3 transcript levels in QM-PDAC tumours." (PMID 30018740, 2018). "In this study, we demonstrate that SLC2A3 is a direct functional target of miR-129-5p in GC cells and the miR-129-5p/SLC2A3 axis plays important roles in the reprogramming of glycometabolism for tumor bioenergetics and biosynthesis, thus influencing GC cell growth." (PMID 29867504, 2018). "Other genes within the top rank have been recently involved in cancer progression, like the case of SLC2A3 (GLUT3) a glucose transporter that mediates glucose utilization and glycogenolysis, which is induced during epithelial-mesenchymal transition and promotes tumor cell proliferation." (PMID 30537927, 2018). "SLC2A3 exhibited a strong correlation with inflammatory gene expression, and its upregulation induces an inflammatory microenvironment through CXCL8-mediated activation of tumor-associated macrophages, subsequently promoting tumor cell progression and metastasis." (PMID 38778609, 2025).
tumor (continued). "Integrating these findings with clinical data from TCGA, it was observed that patients with elevated SLC2A3 expression had a reduced overall survival rate and higher expression levels were noted in patients with advanced T and N stages, pathologic grade, clinical grade, and tumor grade." (PMID 38625978, 2024). "SLC2A3, a membrane proteins, could inhibit tumor growth by up-regulating miR-184." (PMID 37189176, 2023). "Furthermore, SLC2A3 expression strongly correlated with tumor-infiltrating lymphocytes in HNSCC." (PMID 36247875, 2022). "SLC2A3 could serve as a potential prognostic biomarker for tumor immune infiltration in HNSCC." (PMID 36247875, 2022). "Notably, correlation analyses based on the FUSCC cohort suggested that only SLC2A3 was highly expressed in specimens from tumours with poor differentiation, specimens from mucinous-type tumours and specimens from right side tumours." (PMID 32873793, 2020). "Furthermore, it has been shown that SLC2A3 induces tumor cell proliferation in NSCLC." (PMID 32536039, 2020). "SLC2A3 (alias GLUT3) encodes a glucose transporter with a five-fold higher affinity for glucose than its ubiquitous family member GLUT1, making its expression an advantage in glucose-poor microenvironments with high glucose demands, such as in certain tumour environments." (PMID 32580154, 2020). "While broad level gain of 12p in TGCTs appears likely to confer the pluripotent phenotype for initiation of tumourigenesis, the focal amplification of the region containing SLC2A3 may grant a proliferative advantage in progression and development of the tumour." (PMID 32580154, 2020). "We found that SLC2A3 was significantly higher in both protein and mRNA levels in HNSC tumor tissues than in normal tissues." (PMID 38778609, 2025). "Moreover, the expression levels of SLC2A3 have been identified as a significant prognostic marker for disease-free, relapse-free, and overall survival, with higher expression levels correlating with poorer disease-free survival and more aggressive tumor characteristics." (PMID 38625978, 2024). "We investigated the expression of SLC2A3 and ASNS in tumor and normal groups using the R package, and consistently observed high expression levels of SLC2A3 (p = 0.001) and ASNS (p = 2.708e-15) in the tumor group." (PMID 37710311, 2023). "In CRC, activation of the SLC2A3-YAP signaling pathway is a master activator that reprograms tumor metabolism and thus promotes tumor metastasis." (PMID 37621680, 2023). "Using human or mouse-derived healthy and tumor cells, we uncovered that TRPM7 regulates SLC2A3 in a conserved manner." (PMID 36878949, 2023). "In particular, we identified a specific signature of glycolysis-related genes in BRAF-like tumours, which display the overexpression of SLC2A1, SLC2A3, HK3, PFKFB3, PKM, LDHA and SLC16A3 (alias Mct4, the membrane channel regulating lactate efflux)." (PMID 37198319, 2023). "In contrast, some genes such as SLC2A3 and RORA are highly expressed in other cells except tumor cells." (PMID 37496994, 2023). "The results showed that the mRNA and protein expression levels of SLC2A3 were significantly increased in tumor tissues, while the expression level of POU2F2 was significantly decreased in tumor tissues." (PMID 38026928, 2023). "A lower differentiation grade tumor is implied by overexpression of SLC2A1, SLC2A5, SLC2A10, SLC2A11and lower levels of SLC2A3, SLC2A6, SLC2A9, SLC2A12, and SLC2A14, emphasizing the possibility of these molecular roles for predicting the course of the tumor." (PMID 36518662, 2022). "LUAD tumor tissues showed higher mRNA expressions of SLC2A1, SLC2A5, and SLC2A12 and lower expressions of SLC2A3, SLC2A4, SLC2A6, SLC2A9, and SLC2A14." (PMID 36518662, 2022). "Similarly, SLC2A3 overexpression in triple-negative breast cancer could activate inflammatory M1 tumor-associated macrophages resulting in the aggressiveness of tumor cells." (PMID 36247875, 2022).
tumor (continued). "According to data from the UALCAN database, LUAD patients’ tumor tissues had hypomethylation of SLC2A1, SLC2A2, SLC2A5, SLC2A6, SLC2A7, SLC2A11 and hypermethylation of SLC2A3, SLC2A10, and SLC2A14 compared to normal tissues." (PMID 36518662, 2022). "Reportage of tumor HiF status was calculated from the averaged, normalized levels of hypoxia response genes: Glut1 (SLC2A1), Glut3 (SLC2A3), ADM, VLDLR, and VEGFA." (PMID 34681642, 2021). "SLC2A3 signal was localized in the cell membrane, and SLC2A3 protein expression was remarkedly higher in CRC compared with adjacent non-tumor colorectal mucosa tissues." (PMID 34211835, 2021). "Hypoxia is a key feature of the tumor microenvironment and tumor infiltrated NK cells are enriched for hypoxia signatures, including expression of HK2, SLC7A5, SLC2A3, and KDM3A." (PMID 34177887, 2021). "However, Cav-1 regulates glucose metabolism in tumor cells mainly by regulating glucose transporter 3 (GLUT3/SLC2A3) uptake of glucose, which leads to increased aerobic glycolysis and increases intracellular ATP production, thus maintaining the growth and survival of tumor cells." (PMID 34955837, 2021). "We observed that 13C-adenosine, 13C-cytidine, 13C-guanosine and 13C-uridine were dramatically reduced in HCT116 tumours with SLC2A3 silencing, whereas these 13C-labelled metabolites were significantly upregulated in RKO tumours with forced GLUT3 expression." (PMID 32873793, 2020). "Therefore, SLC2A3 may be a potential prognostic biomarker for these tumours." (PMID 32873793, 2020). "According to Western blot, in the tumor tissues from mice injected with cells that were transfected with oe-LINC01094, the protein levels of SLC2A3 were increased while sh-LINC01094 led to the opposite tendency (all p < 0.05)." (PMID 33173535, 2020). "During this process, genes such as SOD2, MMP19, SLC2A3, and SLPI were also upregulated, all of which were related to the invasion and migration of tumor cells." (PMID 31487431, 2019). "FDG is primarily transported by SLC2A1 and SLC2A3, which suggests that FDG uptake by tumor cells will be different depending on different expression levels of glucose transporters." (PMID 28978124, 2017). "HEYL, SLC2A3, and FBN1 were found to mediate tumor progression and chemoresistance mainly by facilitating angiogenesis and EMT, while CERCAM, ANXA1, and SPOCD1 promoted tumor progression through the PI3K/AKT and EGFR signaling pathways." (PMID 39033778, 2024). "Consistent with the in vitro data, in SLC2A3-overexpressing OCI-LY1 xenograft models, the combination of 5-azacytidine and vitamin C significantly improved the tumor-suppressive effect of cisplatin compared with that in empty vector-transduced OCI-LY1 xenograft models." (PMID 37138342, 2023). "This was further confirmed in vivo, as TRPM7KO tumor exhibited less SLC2A3 expression but not SLC2A1." (PMID 36878949, 2023). "In our study, we show that transcriptional levels of SLC2A1, SLC2A5 are upregulated and those of SLC2A3, SLC2A6, SLC2A9, SLC2A14 are downregulated in LUAD patients, supporting the role of SLC2A1, SLC2A5 as oncogenes and SLC2A3, SLC2A6, SLC2A9, SLC2A14 as tumor suppressor genes." (PMID 36518662, 2022). "Furthermore, qRT-PCR analysis revealed that SLC2A3, FOXO3, EGFR and GPC1 were upregulated in tumor samples." (PMID 33962639, 2021). "NICI and SLC2A3 RNA were significantly up-regulated in tumor samples from ccRCC patients, but not in nonclear cell tumors, supporting the strong association with the HIF pathway." (PMID 31690629, 2020). "We have postulated that SLC2A3 might regulate the progression of GC by promoting glycolysis reprogramming, activating the STAT3 signaling pathway, and increasing tumor microenvironment macrophage infiltration and M2 subtype transition." (PMID 33061855, 2020). "However, the correlation of KLF4 mRNA levels with the mRNA levels of VEGFA, SLC2A3 and HK2 was only moderate to weak in the analyzed tumor samples (R = 0.5044; R = 0.3348; R = 0.4416)." (PMID 32245394, 2020).
tumor (continued). "Similarly, CD49fhiCD24low tumor cells exhibited significantly lower expression of EGR1 (−20-fold, p = 0.02), glucose transporter 3 (SLC2A3; −50-fold, p = 0.03), and GAPDH (−100-fold, p = 0.01) than benign cell counterparts." (PMID 26316122, 2015). "Furthermore, SLC2A3, SLC2A6, SLC2A9, SLC2A12, and SLC2A14 levels were lower in patients with advanced tumor stages, suggesting that these genes might act as a barrier to the progression of LUAD." (PMID 36518662, 2022). "Additionally, SLC2A3-AAV (AAV-SLC2A3-KD) markedly suppressed tumor growth compared to negative controls." (PMID 33061855, 2020). "We found that SLC2A3, a key transporter in the glycolysis, showed a significant positive correlation with UBD in the network, suggesting that UBD may enhance glucose uptake by upregulating the expression of these transporters, thereby providing sufficient energy for tumor cells." (PMID 40692714, 2025). "The predictive capacity of SLC2A3-SDHA expression was consistent, regardless of the treatment modality (RT or CRT) or the local extension of the tumor (cT1-T2 or cT3-T4)." (PMID 40141095, 2025). "Glucose transporters include SLC2A1, SLC2A2, SLC2A3, and SLC2A4, and we found the expression of SLC2A1 was significantly upregulated in HCC tumor, contrast with that in adjacent non-tumor tissues (from TCGA Database)." (PMID 37443106, 2023). "Among genes differentially expressed between tumor samples with and without necrosis, a substantial number of hypoxia-related genes were found to be up-regulated, such as IL6, CXCL8 (IL8), SERPINE1 as well as genes involved in glycolysis (SLC2A3, LDHA)." (PMID 26485755, 2015).